S100A2 (S100 calcium binding protein A2)
Diseases named in the same sentence as S100A2 in open-access papers (continued):
Sharing a sentence is not in itself a finding about the gene and the disease.
oral cancer (11 papers, 2010 to 2026). "High cytoplasmic S100A2 and/or total S100A2 expression levels were identified as predictors of recurrence risk in patients with oral cancer." (PMID 35042454, 2022). "For instance, S100A2 expression loss serves as an independent prognostic marker in early-stage oral cancer patients at high risk of recurrence." (PMID 33750880, 2021). "Our study underscores the biological relevance of nuclear loss of S100A2 expression and its cytoplasmic accumulation in oral cancer." (PMID 25591983, 2015). "A unique translational aspect of our study is validation of S100A2 as prognostic marker in two independent cohorts (Canadian and Indian) suggesting this protein is likely to find widespread utility in clinical practice for identifying oral cancer patients at high risk of disease recurrence." (PMID 25591983, 2015). "A unique translational aspect of our findings is the validation of S100A2 as a prognostic marker in two independent cohorts (Canadian and Indian) suggesting this protein is likely to find widespread utility in clinical practice for identifying oral cancer patients at high risk of disease recurrence." (PMID 25591983, 2015). "Studies found that the expression of S100A2 was decreased in early-stage oral cancer cells and recurrent nasopharyngeal cancer, however other investigators suggest S100A2 upregulation in HNSCC." (PMID 26097874, 2015). "Despite these reports, the clinical relevance of S100A2 expression as a prognostic marker for oral cancer patients remains to be determined." (PMID 25591983, 2015). "S100A2 has also been reported to play an inhibitory role in the development of oral cancers." (PMID 41513619, 2026). "Notably, cytoplasmic S100A2 expression emerged as a poor prognosticator in OSCC underscoring the clinical significance of S100A2 in oral cancer." (PMID 25591983, 2015). "Importantly, cytoplasmic S100A2 emerged as an independent predictor of recurrence in OSCC patients suggesting its potential to serve as a prognostic marker in oral cancer patients." (PMID 25591983, 2015). "We hypothesized that alterations in S100A2 sub-cellular localization in cytoplasm or nucleus could influence oral cancer pathogenesis and may correlate with clinical outcome in these patients." (PMID 25591983, 2015). "In conclusion, we demonstrate S100A2 is overexpressed in oral cancer." (PMID 25591983, 2015). "One limitation of our study is that it does not provide mechanistic insight into the role of S100A2 in oral cancer." (PMID 25591983, 2015).
ovarian carcinoma (10 papers, 2015 to 2023). A malignant neoplasm originating from the surface ovarian epithelium. "S100A2 expression is upregulated in patients with ovarian cancer, and high S100A2 expression is associated with advanced clinical stage and unfavorable prognosis in vivo." (PMID 35885660, 2022). "S100A2, a member of the largest subfamily of calcium-binding EF-hand type proteins, has been found to be related to poor prognosis in patients with ovarian cancer." (PMID 37525249, 2023). "High expression of S100A2 is also significantly correlated with worse OS in patients with ovarian cancer." (PMID 35042454, 2022). "Expression levels of GJB2, S100A2 and SPOCK2 were increased in ovarian cancer and their upregulation was linked to poor prognosis of patients with ovarian cancer." (PMID 31794425, 2019). "In accordance, in our study, for all ovarian cancer patients, S100A2 mRNA expression was correlated with poor prognosis." (PMID 30558666, 2018). "Higher tissue expression of S100A2 was significantly correlated with worse overall survival in ovarian cancer patients, and S100A2 protein expression in saliva was observed to be higher in oral squamous cell carcinoma patients in comparison to other oral potentially malignant disorders." (PMID 32344524, 2020). "In this study, based on comprehensive expression analysis and survival analysis, three genes (GJB2, S100A2 and SPOCK2) were identified as key genes which may be associated with progression of ovarian cancer." (PMID 31794425, 2019). "Taken together, GJB2, S100A2 and SPOCK2 might be three key genes in mediating tumor stage progression of ovarian cancer and causing poor prognosis." (PMID 31794425, 2019). "The role of S100A2 in ovarian cancer has rarely been explored." (PMID 30558666, 2018). "Moreover, other studies identified S100A2 up-regulation in a number of other malignancies, such as pancreas adenocarcinoma and ovarian cancer, among others." (PMID 26097874, 2015). "Subsequently, we introduced the ovarian cancer data other than TCGA to further assess the survival effects of GJB2, S100A2, SPOCK2 and TGM1 on prognosis (OS) by Kaplan-Meier plotter." (PMID 31794425, 2019). "Ovarian cancer patients with higher expression of GJB2, S100A2 and SPOCK2 showed better OS, which was identical with the analytic results obtained from TCGA cohort." (PMID 31794425, 2019). "High expression of GJB2, S100A2, SPOCK2, TGM1or EPS8 indicated a poor OS of patients with ovarian cancer, whereas ovarian cancer patients with higher expression of ADAMDEC1, CHEK1, EGFL6, FAM181A, FOXA2, LYPD1, PART1 or XPR1 possessed better OS." (PMID 31794425, 2019). "All these reports together with our current analytic results of expression and survival analysis demonstrate that GJB2, S100A2 and SPOCK2 may be three key oncogenes in the progression of ovarian cancer." (PMID 31794425, 2019).
squamous cell carcinoma (9 papers, 2004 to 2025). A carcinoma arising from squamous epithelial cells. "Most squamous cell carcinomas are associated with an unfavorable prognosis, depending on the reduced expression of S100A2." (PMID 35885660, 2022). "We performed immunofluorescence staining to investigate the subcellular distribution of S100A2 in A-431 epidermoid carcinoma cells, U2OS osteosarcoma cells, and GBM cells." (PMID 38684596, 2024). "Ectopic expression of S100A2 in the human malignant squamous cell carcinoma cell line KB results in significant inhibition of proliferation, migration, and invasion, which can be negatively regulated by cyclooxygenase-2 (COX-2) expression in vitro." (PMID 35885660, 2022). "S100A2 expression has been observed in various squamous cell carcinomas, including those of conjunctival origin." (PMID 35885660, 2022). "Regarding S100A2 action in squamous cell carcinoma, S100A2 negatively regulates cell motility in squamous cell carcinoma in vivo." (PMID 35885660, 2022). "Another study revealed that, in primary squamous cell carcinoma of the larynx, the high expression of S100A2 appeared to be a significant independent predictive factor for favorable survival in vivo." (PMID 35885660, 2022). "S100A2 expression appears to differ from that at the original site of squamous cell carcinoma." (PMID 35885660, 2022). "Although it is necessary to clarify the detailed molecular mechanisms involving S100A2 in squamous cell carcinoma, the spectrum of action of S100A2 might have antitumor effects on the development of squamous cell carcinoma." (PMID 35885660, 2022). "Indeed, S100A2 regulates in vitro squamous cell carcinoma migration by exerting a favorable inhibitory effect on metastasis, indicative of its negative regulatory effects on the migration of some other cells." (PMID 33750880, 2021). "Lung adenocarcinoma (ADC), squamous cell carcinoma (SCC), large cell carcinoma, and atypical carcinoids show high S100A2 expression, while small cell lung carcinoma (SCLC) lacks S100A2 expression." (PMID 41164170, 2025). "In squamous cell carcinoma, FADU and RPMI-2650 cell lines showed high and low levels of S100A2, respectively, and S100A2 expression had a significant inhibitory effect on cell activity." (PMID 34148033, 2021). "Similarly, by using squamous cell carcinoma (SCC) as a cancer model, it was found that overexpressed S100A2 possesses a profound effect in inhibiting cell migration and invasion in vitro and in vivo." (PMID 25874882, 2015).
glioma (6 papers, 2021 to 2025). A benign or malignant brain and spinal cord tumor that arises from glial cells (astrocytes, oligodendrocytes, ependymal cells). "High S100A2 expression is significantly associated with poor prognosis in patients with low-grade glioma in vivo." (PMID 35885660, 2022). "Glioma exhibited a moderate S100A2 signal, while certain cell components of normal cerebral cortex and hippocampus tissues displayed strong signals." (PMID 38684596, 2024). "S100A2 expression is also related to high tumor grade and is frequently observed in high-clinical-stage gliomas." (PMID 35885660, 2022). "CpG methylation has been observed in gliomas, and it negatively regulates S100A2 expression in vivo." (PMID 35885660, 2022). "Low-grade glioma is a progressive malignant brain tumor in which S100A2 is upregulated." (PMID 35885660, 2022). "Similar to low-grade glioma, in which the S100A family genes play vital roles in tumor progression mostly via the IL-17 signaling pathway, our data implied that S100A2 might play a critical role in endometrial carcinoma initiation and progression through similar mechanisms." (PMID 35042454, 2022). "When GII/GIII-IDHmut gliomas were compared to GIV gliomas, significant differences of DNA methylation in the promoters of S100A2, RAB36, RIN1, UPP1, and VIM were found." (PMID 36850002, 2023). "There are relatively few studies on S100A2 and S100A3 genes in glioma immunity, and there is no sufficient evidence to show their specific role in glioma immunity at present." (PMID 34148033, 2021).
prostate carcinoma (6 papers, 2015 to 2026). A carcinoma that arises from epithelial cells of the prostate gland. "S100A6 and S100A2 are the two calcium-binding proteins that are mostly down-regulated in prostate cancer, and the underlying mechanism responsible for it appears to involve hypermethylation of S100A6 and S100A2." (PMID 36765652, 2023). "Lower S100A2 expression is associated with favorable clinical outcomes in prostate cancer in vivo." (PMID 35885660, 2022). "Immunostaining analysis reveals loss of S100A2 expression in prostate cancer in vivo." (PMID 35885660, 2022). "Although benign prostate hypertrophy and prostatitis display increased S100A2 expression, low-grade prostate cancer exhibits reduced expression of S100A2 in vivo." (PMID 35885660, 2022). "It should be noted that S100A2 promoter hypermethylation has previously been demonstrated in prostate cancer, but considerable levels of methylation were also present in some non-malignant prostate tissues." (PMID 26097874, 2015). "DNA methylation has been postulated as a mechanism underlying the downregulation of S100A2 in prostate cancer, and S100A2 methylation has also been observed in 75% of nonmalignant tissues and 100% of benign prostate hypertrophy cases." (PMID 35885660, 2022). "In support of this, S100A2 transcription repression in breast, lung, and prostate cancer cells and cell lines was shown to be mediated at least in part by site-specific methylation in the promoter region, similarly to a number of known and putative tumor suppressor genes." (PMID 26097874, 2015). "While the methylation status of S100A2 has been examined extensively in breast, lung, and prostate cancers, it has not been investigated in other cancers." (PMID 26097874, 2015).
atopic dermatitis (5 papers, 2021 to 2025). "The role of S100A2 in inflammation is also suggested by the increased expression levels of S100A2 found in the skin of patients with atopic dermatitis and psoriasis." (PMID 39766257, 2024). "S100A2 was also involved in the development of inflammatory reactions, atopic dermatitis, drug eruption, psoriasis, delayed wound healing, and asthma." (PMID 35885660, 2022). "S100A2 is highly upregulated in the epidermis under inflammatory conditions and in drug eruptions, in addition to inflammatory skin diseases such as atopic dermatitis and psoriasis." (PMID 35885660, 2022). "S100A2 expression also significantly increased in the skin of patients with atopic dermatitis and psoriasis." (PMID 33750880, 2021). "However, S100A2 is expected to be a positive driver for the development of inflammatory reactions in atopic dermatitis, psoriasis, drug eruption, and asthma." (PMID 35885660, 2022). "S100A2 also reflects the severity of atopic dermatitis, as a result of keratinocyte damages." (PMID 34299145, 2021). "The methylation of genes like S100A2 and FCERIG in atopic dermatitis or FLG in eczema illustrates how modifications affect immune pathways and skin integrity." (PMID 40182929, 2025). "However, S100A2 is not a specific biomarker because S100A2 is also upregulated in atopic dermatitis and psoriasis patients." (PMID 34299145, 2021). "In addition, histological analysis of S100A2 and HMGB1 reflects the severity of drug eruption, however, they could not reflect the specificity of drug eruption, because they are increased in other inflammatory skin diseases, such as atopic dermatitis and psoriasis." (PMID 34299145, 2021).
cervical cancer (5 papers, 2015 to 2024). A primary or metastatic malignant neoplasm involving the cervix. "Moreover, HIF1A and S100A2 are upregulated and can possibly account for miR-21 overexpression to explain in part the aggressive cervical cancer phenotype progression." (PMID 38612895, 2024). "This could involve exploration of whether overexpressed S100A2 antagonizes PD-L1 inhibitor action in vitro and in cervical cancer metastasis animal model." (PMID 37653224, 2024). "Using cervical cancer metastasis animal model, whether S100A2 is a key cervical cancer metastasis driver and if the level of S100A2 affects the efficacy of pembrolizumab could be directly revealed." (PMID 37653224, 2024). "This gap could be filled by future experiments examining whether the overexpression of S100A2 replicates the effects of hypoxia in driving an aggressive cervical cancer phenotype and if its overexpression counteracts the action of PD-L1 inhibitor pembrolizumab in reducing cancer phenotype." (PMID 37653224, 2024). "As less than 60% of cervical cancers express PD-L1, the mechanism of S100A2 upregulation driving PD-L1 expression and leading to immunotherapy resistance necessitates further exploration, specifically whether S100A2 is associated with patient outcomes linked to PD-L1 expression." (PMID 37653224, 2024). "In cervical cancer progression, both AP-1, hypoxia-inducible factor 1 alpha (HIF1A), and S100A2, which are major mediators of cell response to hypoxia, are associated with the carcinogenesis process." (PMID 38612895, 2024). "Similarly to S100A2 and S100A11, S100A14 appears to have a complex role in cancer, showing overexpression in breast, liver and cervical cancer, but downregulation in other cancers such as rectal, kidney, colon and esophageal cancers." (PMID 37627239, 2023). "Cervical cancer used as a positive control showed nuclear and cytoplasmic expression of S100A2 protein, while no immunostaining was observed in tissue sections used as negative controls where the primary antibody was replaced by isotype specific IgG." (PMID 25591983, 2015). "Though high S1002A2 may predict poor prognosis in endometrial carcinoma, the functions of S100A2 in cervical cancer have not been well established yet." (PMID 37653224, 2024).
colon carcinoma (5 papers, 2020 to 2025). "S100A2 gene expressions in colon cancers have also been reported and are associated with poor OS and DFS of CRC patients." (PMID 33294444, 2020). "S100-A2 is downregulated in some tumors and upregulated in others (including colon carcinoma), thus high protein expression levels cannot be directly correlated to tumor formation." (PMID 38473953, 2024). "Studies showed that activation of the S100A2/GLUT1 axis can promote colon cancer progression by regulating the glycolytic process." (PMID 34148033, 2021). "Several S100 proteins, including S100A1, S100A2, S100A4, and S100A11, were found in colon carcinomas with more aggressive disease and worse clinical outcomes." (PMID 41134679, 2025).
lung adenocarcinoma (5 papers, 2004 to 2025). A carcinoma that arises from the lung and is characterized by the presence of malignant glandular epithelial cells. "The downregulation of S100A2 suppresses TGF-β1-mediated epithelial–mesenchymal transition (EMT) in lung adenocarcinoma cells in vitro." (PMID 35885660, 2022). "Positive S100A2 expression is significantly related to a high frequency of lymph node metastasis in lung adenocarcinoma in vivo." (PMID 35885660, 2022). "Of note, GPC1 and S100A2 have been previously reported together as candidate biomarkers associated with unfavorable prognosis in lung adenocarcinoma without however relationship between the two molecules inferred." (PMID 36944188, 2023).
psoriasis (5 papers, 2021 to 2024). An autoimmune condition characterized by red, well-delineated plaques with silvery scales that are usually on the extensor surfaces and scalp. "Expression levels of S100A2 gene is markedly upregulated in the involved skin of inflammatory dermatoses such as psoriasis and atopic dermatitis, and correlate positively with the severity of inflammatory skin disorders." (PMID 37346040, 2023). "To ensure human relevance, we examined the mRNA expression of S100A2 in other human skin diseases such as psoriasis and AD using public microarray data sets." (PMID 33750880, 2021). "The expression levels of several S100 proteins, such as S100A2, S100A7, S100A8/S100A9, S100A12, and S100A15, are significantly up-regulated in psoriasis-involved skin." (PMID 37346040, 2023).
asthma (4 papers, 2022 to 2025). "Another study found increased salivary S100A2 levels in patients who had long-term uncontrolled asthma, suggesting that airway inflammatory diseases are also associated with S100A2-mediated pathogenesis." (PMID 41258511, 2025). "Consistently, S100A2 levels are increased in the saliva of patients with uncontrolled asthma, suggesting that lung inflammatory diseases are also associated with S100A2-mediated pathogenesis." (PMID 35885660, 2022).